HTD2 (hydroxyacyl-thioester dehydratase type 2)
Description:
Mitochondrial 3-hydroxyacyl-thioester dehydratase, which may be involved in fatty acid biosynthesis.
Tractability: No criterion of Open Targets' tractability assessment is met for any kind of drug.
Gene: Protein-coding gene on chromosome 3 (58,306,262 to 58,320,193, forward strand). Ensembl gene ENSG00000255154.
Subcellular location: Mitochondrion
Subcellular location (Human Protein Atlas): Mitochondria; Nucleoli
Pathways (Reactome):
Metabolism: Fatty acyl-CoA biosynthesis
Gene Ontology:
Molecular function: (3R)-hydroxyacyl-[acyl-carrier-protein] dehydratase activity; 3-hydroxyacyl-CoA dehydratase activity
Biological process: fatty-acyl-CoA biosynthetic process
Cellular component: mitochondrion; mitochondrial matrix
Homologues: Orthologues: macaque RPP14 (98% identical), chimpanzee HTD2 (91% identical), dog HTD2 (82% identical), rabbit HTD2 (80% identical), guinea pig HTD2 (77% identical), mouse Htd2 (74% identical), rat Rpp14 (71% identical), pig HTD2 (54% identical), tropical clawed frog HTD2 (53% identical).
Diseases named in the same sentence as HTD2 in open-access papers:
HTD2 is named in the same sentence as 4 diseases in open-access papers, as found by Europe PMC text mining. Sharing a sentence is not in itself a finding about the gene and the disease. The quoted sentences say what the papers report.
Headache (1 paper, 2018). Cephalgia, or pain sensed in various parts of the head, not confined to the area of distribution of any nerve. "We identified numerous genes associated with headache, both temporal and other types: POFUT2 in CD4 cells, and SLC35F6, HTD2, ZNF708, KLRC4-KLRK1 and JMJD7 in CD8 cells." (PMID 30037347, 2018).
Infertility (1 paper, 2025). "Third, species-specific genes like human HTD2 represent promising targets for investigating lipid-related infertility." (PMID 41516270, 2025).
Insulin resistance (1 paper, 2021). Increased resistance towards insulin, that is, diminished effectiveness of insulin in reducing blood glucose levels. "Recent results support α-lipoic acid as an effective mitochondrial nutrient to improve insulin resistance in Htd2 knockdown adipocytes." (PMID 34371841, 2021).
infection (1 paper, 2013). The state of being infected such as from the introduction of a foreign agent such as serum, vaccine, antigenic substance or organism. "The expression of D3 and D14/HTD2 was suppressed in rice plants infected with RGSV, implying that the SL signaling process is repressed by RGSV infection." (PMID 24151491, 2013).